MAP2K1 (mitogen-activated protein kinase kinase 1)
Diseases named in the same sentence as MAP2K1 in open-access papers (continued):
Sharing a sentence is not in itself a finding about the gene and the disease.
tumor (continued). "Furthermore, key regulatory genes in the MAPK pathway, such as MAP2K1, MAP2K2 and SHC1, were upregulated in tumour cells positive for the three integrin receptors." (PMID 38279519, 2024). "Collectively our results suggested that EGFR, MAP2K1, mTOR, TEAD1, and YAP1 could mediate invasive tumor phenotypes and worsen prognoses via mechanisms involving both T-cell exclusion and dysfunctional phenotypes." (PMID 35655775, 2022). "Hence, we evaluated the potential role of EGFR, MAP2K1, mTOR, and YAP1 in promoting the infiltration of tumor immune cells within the TME." (PMID 35655775, 2022). "Collectively our results suggested that EGFR, MAP2K1, mTOR, TEAD1, and YAP1 could mediate invasive tumor phenotypes and produce worse prognoses via mechanisms involving both the T-cell exclusion and dysfunctional phenotypes." (PMID 35655775, 2022). "Interestingly, it has been demonstrated that copper binding to the mitogen-activated protein kinase kinase 1 (MAP2K1) promotes the activation of the mitogen-activated kinase (MAPK) pathway, which has a prominent role in promoting tumor growth." (PMID 32041110, 2020). "Furthermore, four genes (MAP2K1, EIF4EBP1, MAPK8, and RPS6KB1) were enriched in ERBB signaling pathway, required for GBM stem cell proliferation, and three genes (MAP2K1, MAPK8, and RPS6KB1) were enriched in NFAT pathway, promoting tumor angiogenesis." (PMID 28056026, 2017). "MEK1/2 (MAP2K1/K2), the canonical targets of MEK inhibitors, are dual-specificity threonine/tyrosine kinases that are integral in the activation of the RAS/RAF/MEK/ERK pathway and are often upregulated in a variety of tumor cell types." (PMID 26439693, 2015). "MAP2K1 was not mutated in any TMS2 cases; however, mutations were detected in 7% of TMS3 tumours." (PMID 38650367, 2024). "As a consequence, treatment with the Mitogen-Activated Protein Kinase Kinase 1/2 (MEK1/2) inhibitor trametinib releases transcriptional stalling at the MYF4 promoter, followed by a widespread MYF4-induced change in SE landscape, myogenic differentiation and reduced tumor growth in mouse models." (PMID 37345159, 2023). "In addition, copper can affect mitogen-activated protein kinase kinase 1 (MEK1) and mitogen-activated protein kinase kinase 2 (MEK2) and enhance their phosphorylation of ERK1 and ERK2 in a dose-dependent manner, further promoting tumor cell proliferation." (PMID 37427098, 2023). "In addition, we queried the phosphorylation status of the proteins and found that mTOR and MAP2K1 showed consistent increases (p<0.05) in dephosphorylation, while EGFR was consistently hyper-phosphorylated (p<0.05) in higher tumor grades (normal, grades I~III)." (PMID 35655775, 2022). "Putative oncogenic and targetable mutations could be found in individual tumor samples in FGFR2 (SNUC, SNSCC non-keratinizing), FGFR3 (SNSCC-associated with ISP), MAP1K2 (SNAC), MET (ISP-associated SNSCC), MAP2K1 (SNAC) and HRAS (SNSCC keratinizing and ITAC)." (PMID 34885191, 2021). "Tumor samples exhibited slightly higher expression than metastatic samples, suggesting that PI3K3CA is involved in tumorigenesis (As shown, MAP2K1 and PIK3CA expressions did not significantly increase in metastasis." (PMID 41009348, 2025). "For the two MAPK inhibitors (selumetinib and trametinib) no differential expression of their targets (MAP2K1 and MAP2K2) was observed between tumor and normal tissue." (PMID 34200770, 2021). "Besides, the correlation between the miR-181c overexpression after -and possibly induced by- the MAP treatment and the absence of the tumor relapse, can be partially explained considering that among its putative targets figure genes regulating the cell cycle, like GATA6, MAP2K1, PPM1A and Notch2." (PMID 26062442, 2015).
cancer (448 papers, 2005 to 2026). A tumor composed of atypical neoplastic, often pleomorphic cells that invade other tissues. "In-frame deletions comprise only 4.3% of all MAP2K1 mutations reported across all human cancers, and only 0.2% of all BRAF mutations; consequently, they remain relatively understudied." (PMID 37079639, 2023). "The RAS/MAP2K1 pathway is one of the most commonly mutated oncogenic pathways in cancer and the activating mutations present in AVMs are also often found within malignancies." (PMID 37422456, 2023). "Drug sensitivity analysis shows that in contrast to the association of YAP1/EGFR/MAP2K1 with drug resistance, high expressions of mTOR are favorable to cancer chemotherapy." (PMID 35655775, 2022). "MAP2K1 mutation is a rare oncogenic alteration, and is reportedly associated with the development and prognosis of cancers." (PMID 35186740, 2022). "MAP2K1 F53 mutations have been previously documented in cancer patients and validated as functional driver mutations." (PMID 36418460, 2022). "Mutations of MAP2K1 have been reported in several human cancers, especially melanoma, Langerhans histocytosis, hairy cell leukemia and lung adenocarcinoma." (PMID 34046359, 2021). "Alterations of mitogen-activated protein kinase kinase 1 (MEK1) are commonly associated with tumorigenesis, and MEK1 is thought to be a suitable targeted therapy for various cancers." (PMID 34526571, 2021). "Others, such as FN1, EP300, CASP8, EGF and MAP2K1, which were associated with the pathways involved in cancer, were also hub-node genes." (PMID 31501464, 2019). "Finally, DD1522 displayed a deletion in the MAP2K1 gene, which is affected in a high number of cancers and a previously reported hot spot mutation in GNAS (R201H)." (PMID 35954444, 2022). "Interestingly, we found that mutations in this region of EGFR, BRAF, ERBB2, and MAP2K1 were mutually exclusive, which is consistent with a previous report that suggested one driver mutation is sufficient cancer initiation or development." (PMID 32757330, 2020). "Integrating with clinical trial evidence, 33 unique cancer‐linked genes were drug targets under clinical trial development, with LIPA and MAP2K1 being targets for already launched anticancer drugs." (PMID 41216857, 2025). "The dual specificity mitogen-activated protein kinase kinase 1 (MEK1) is a critical node in the RAS-RAF-MEK-ERK signaling pathway, frequently dysregulated in cancers due to mutations in upstream regulators." (PMID 40949115, 2025). "This novel insight not only expands our understanding of the molecular underpinnings of HSCC but also positions MAP2K1 as a potential therapeutic target in MALAT1-driven cancers." (PMID 39319867, 2025). "MAP2K1 plays a role in the development of human cancers and is a transducer of a growth factor receptor." (PMID 40365251, 2025). "Variants classified as pathogenic across all five tools were cross-referenced with known cancer genes, identifying high-confidence mutations in FLNC, MAP2K1, and ABCA1." (PMID 41373405, 2025). "Experimental studies have shown that overexpression of activated MAP2K1 can enhance the proliferation of cancer cells and confer drug resistance on cells." (PMID 40587753, 2025). "Gene-centric analyses highlight four cancer-relevant loci MAP2K1, FLNC, ABCA1, and TUBB3 as key targets of methylation deregulation, each exhibiting distinct CpG methylation patterns linked to their known biological roles in tumorigenesis." (PMID 41373405, 2025). "Using the Oncomine database, we compared MAP2K transcription in 20 cancers and normal tissues: mRNA expression of MAP2K1/3/4/6 was significantly lower, and MAP2K2 was significantly higher, in LIHC tissue (P < .05)." (PMID 40587753, 2025).
cancer (continued). "Many recently developed cancer therapies target this pathway, including inhibitors of mitogen-activated protein kinase kinase 1 and 2 (MEK 1 and MEK 2)." (PMID 40964318, 2025). "We then performed immunohistochemical staining in cancer tissues and adjacent paracancerous tissues to detect MAP2K1 protein expression." (PMID 39319867, 2025). "While the oncogenic role of MALAT1 has been previously documented in various cancers, the specific involvement of MAP2K1 in the MALAT1-mediated regulatory network within HSCC has not been reported until now." (PMID 39319867, 2025). "The ERK inhibitor ulixertinib shows early efficacy in treating tumors with MAPK pathway alterations, prevalent in 30% of all human cancers due to activating mutations in RAS, BRAF, or MAP2K1 (MEK1)." (PMID 38429288, 2024). "Several of these genes have well-known roles in cell viability and cancer, including MAP2K1 (MEK1), AURKB and CDK7." (PMID 36809237, 2023). "The reported prevalence of BRAF and MAP2K1 in-frame deletions in human cancers is thought likely to be an underestimate since sequencing technologies and analytic tools are designed primarily for identification of point mutations." (PMID 37079639, 2023). "These two hotspots of MAP2K1 deletion in human cancers are orthologous to the regions of recurrent deletion identified in our canine UC cohort." (PMID 37079639, 2023). "The expression levels of MAP2K1 in GC tissues and normal tissues adjacent to cancer were retrieved by starbase database, and the outcomes revealed that MAP2K1 mRNA were significantly higher in GC tissues than in paracancerous tissues." (PMID 36203485, 2022). "Others models have demonstrated sensitivity of cancer cells with MAP2K1 in-frame deletion to MEK inhibition." (PMID 32483240, 2020). "In this study, we analyzed a large number of 10,000 patients with advanced cancers for oncogenic mutations in EGFR, ERBB2, BRAF, and MAP2K1, especially for those located within the kinase domain β3‐αC loop." (PMID 32757330, 2020). "In conclusion, based on a large cohort of cancer patients, our study analyzed mutations in β3‐αC loop in kinase domain of EGFR, ERBB2, MAP2K1, and BRAF, and summarized the drug‐relevant mutations of each gene." (PMID 32757330, 2020). "The Mitogen-activated protein kinase kinase 1/ extracellular signal-regulated kinases 1/2 (MEK/ERK) pathway is known to be survival signaling of cancer cells." (PMID 32433559, 2020). "Other novel, highly scoring gene pair predictions that included cancer associated genes included PARP1 with PBRM1, BRCA2, ARID1A and APC as well as PIK3CA with MAP2K1, ABL1 and EGFR." (PMID 30995217, 2019). "We discovered multiple mosaic-activating variants in 4 genes of the RAS/MAPK pathway, KRAS, NRAS, BRAF, and MAP2K1, a pathway commonly activated in cancer and responsible for the germline RAS-opathies." (PMID 29461977, 2018). "Bosutinib and Trametinib targeting on the MAP2K1/2 were used for cancer stem cell and multi-drug resistance treatment." (PMID 29723215, 2018). "Of noteworthy importance is the upregulated expression of several genes identified as proto-oncogenes, including genes with very well characterized roles in cancer progression such as Map2k1 and Src." (PMID 28874141, 2017). "We also observed several mutations in the MAP kinase signaling pathway (14% of tumors), involving KRAS, NRAS, BRAF, and MAP2K1 oncogenes across multiple cancer types including hematologic, lung, ovarian, duodenal, biliary, and colorectal." (PMID 29100271, 2017). "NRAS mutations activate downstream kinases including RAF and MEK1/2 (MAP2K1/2), and preclinical and early clinical data showed that NRAS-mutant cell lines and tumors of cancer patients are highly sensitive to MEK1/2 inhibitors." (PMID 27613601, 2016). "The drug targeting MAP2K1, Binimetinib, had been launched for cancer treatment (NCT01556568)." (PMID 41216857, 2025).
cancer (continued). "Higher targeting of MAP2K1 by transcription factors may reduce the effectiveness of cancer therapeutics targeting MAP2K1 such as trametinib in males compared to females." (PMID 39107837, 2024). "Many TME-related genes (such as VEGFA, MMP14, CCND1, MAP2K1, SLC2A1) and actin cytoskeleton-associated genes (such as ITGB4, ITGA6, ACTG1, VCL) were downregulated, suggesting a less favorable TME and an altered cytoskeleton network in ISO-treated cancer cells." (PMID 38339062, 2024). "While generally infrequent, oncogenic deletions within MAP2K1 exons 2 and 3 are enriched in a small subset of human cancers including certain melanocytic lesions and particularly pediatric LCH (~30% of cases), and are mutually exclusive from the BRAF V600E variant." (PMID 37079639, 2023). "MAP2K1 activation enables proliferation and survival of cancer cells." (PMID 37897503, 2023). "This includes the K57E variant that we identified in a single canine sample, which corresponds to the most frequently altered MAP2K1 codon identified in human cancers, and which has been associated with emergence of resistance to BRAF monomer inhibitors in human cancer cells." (PMID 37079639, 2023). "As shown in, 9 essential oil compositions could act on CASP3, MAP2K1 and CDC25B, respectively and be associated with solid tumor/cancer." (PMID 35702766, 2023). "Cancer related studies of the RAS/MAP2K1 pathway have led to the development of several FDA approved MEK1 inhibitors which could be repurposed as potential AVM treatments." (PMID 37422456, 2023). "Collectively, this study suggested that NSC765598 has a potential for multi-target inhibition of EGFR/iNOS/mTOR/TGFB1/FGFR/MAP2K1 and could serve as a lead compound for developing new therapeutics for cancer treatment." (PMID 33842373, 2021). "Somatic mutations in the MAP2K1 gene, which encodes MEK1, are associated with arterio-venous malformation (AVM), and constitutively increased MEK1 activity is observed in various cancer types." (PMID 33634164, 2020). "The main downstream signaling pathway of EGFR/HER2 includes the rat sarcoma (RAS)-RAF proto-oncogene serine/threonine protein kinase-mitogen-activated protein kinase kinase 1/2 (MEK1/2)-extracellular signal regulated kinase 1/2 (ERK1/2) pathway controlling cancer development and progression 5-7." (PMID 32398965, 2020). "Of the remaining 17 variants, all but three are accounted for by six genes (BRAF, CBL, MAP2K1, MAP2K2, RAF1, and SOS1) encoding members of the RAS-MAPK pathway, among which nine variants have previously been reported in either congenital disorders or cancer." (PMID 30355600, 2018). "MAP2K1 is part of multiple signaling pathways and many pathways in cancer." (PMID 30261835, 2018). "Of these kinases, MAP2K1, OXSR1 and EPHA3 are implicated in cancer." (PMID 22219723, 2011). "Additionally, trametinib is also recommended by BRAF and MAP2K1 alterations, as well as new molecular evidence, such as G6PD (mutation and high overexpression), CDKN2A (deletion and underexpression) and due to the genetic dependency of MAP2K1 in BRAF-mutant cancer cell lines." (PMID 37207338, 2023). "While the majority of Class 1 (RAF dependent) MAP2K1 mutations are associated with co-mutation in BRAF, NRAS, or NF1, only a small proportion of class 2 (RAF regulated) cases and no class 3 (RAF regulated) cases share these co-mutations in a limited pan-cancer analysis." (PMID 32483240, 2020).
cancer (continued). "We experimentally tested the activating potential of rare mutations identified in 3D clusters in the MAP2K1 and RAC1 proteins, enlarging the number of biologically and potentially clinically significant alleles in these two critical effectors of activated signaling pathways in cancer." (PMID 28115009, 2017). "MAP2K1, a pivotal member of the MAPK family, plays a crucial role in regulating the malignant phenotypes of cancer cells, including proliferation, apoptosis, invasion, and migration." (PMID 39319867, 2025). "Among these genes, seven proteins (MAP2K1, FERMT2, HMGB2, FAF2, STK26, THRAP3, and KRT15) showed significant differences between carcinoma and adjacent tissues (TCGA-HNSC database)." (PMID 39319867, 2025). "Other important cancer-related molecules and pathways were inhibited upon GCV treatment, for example, HIF1A, MAP2K1/2, PI3K, JUN, and HDAC." (PMID 38927982, 2024). "Both MAP2K4 and MAP2K1 are members of the MAPK gene family, and the MAPK pathway is known to be a crucial modulator of the cancer metastasis process." (PMID 38685065, 2024). "This set of highly variable kinases contains known cancer drivers and kinases with inhibitors already used in the clinic as cancer treatment, such as BRAF, AKT, MAP2K1, SRC among others." (PMID 36688815, 2023). "Screening 107 overall survival-related cancer genes and 402 interacting gene pairs, 6 genes: CRLF2, HSP90AA1, MAP2K1, PAFAH1B2, MYCL and SET genes, were identified and a transcriptional score was obtained." (PMID 37897503, 2023). "We explored the cancer genomic dataset from the cBioPortal to analyze genomic alterations in EGFR, iNOS, mTOR, FGFR, TGFR, and MAP2K1 of 10,953 cancer patients (10,967 samples) from different cancer types." (PMID 33842373, 2021). "RhoA and RhoC induce multiple signaling pathways, including the PI3K/Akt pathway, mitogen-activated protein kinase kinase 1/2 (MEK1/2)/ERK1/2 pathway, and ROCK pathway in various cancer cells." (PMID 33406809, 2021). "In addition, NSC765598 displayed favorable properties as a drug lead compound and thus could be considered a novel small molecule with potential for multi-target inhibition of EGFR/iNOS/mTOR/TGFB1/FGFR/MAP2K1 and could serve as a lead compound for developing new therapeutics for cancer treatment." (PMID 33842373, 2021). "For example nocodazol, a colchicine binding site agent was found to simultaneously inhibit various cancer-related kinases, including ABL1, c-KIT, BRAF, MEK1 (MAP2K1), MEK2 (MAP2K2), and MET." (PMID 33671106, 2021). "In total, the identification of hypoxia-dependent RNA–protein complexes such as eif4b and map2k1 and their molecular characterization in cancer signaling should provide insight into new pathways that may modulate translation rates in resistant and hypoxic cancer cells." (PMID 29270287, 2017). "Our method revealed 3D clusters in all three RAS proteins (K/N/H-RAS), RAC1, BRAF, MAP2K1, and MAPK1 in a variety of cancer types." (PMID 28115009, 2017). "Of the top 207 transcripts annotated as ‘cell cycle’ by GO analysis, we focused on nine well-known cell cycle regulators (CCNA2, CCND1, CDK6, CHK1, CHK2, MAPK1, MAP2K1,SKP2, and TFDP1) for further analyses, due to their known functions in cancers." (PMID 26958940, 2016). "In the spleen, 8/84 cancer-related genes were affected in FLT mice compared to AEM controls (P<0.05; up: Cdkn2a; down: Birc5, Casp8, Ctnnb1, Map2k1, Mdm2, NFkB1, Pdgfa)." (PMID 24069384, 2013). "AZD6244 (ARRY-142886), a novel, selective, ATP-uncompetitive inhibitor of mitogen-activated protein kinase kinase 1/2 (MEK1/2), has shown activity in nanomolar concentrations against isolated MEK enzyme and numerous cancer cell lines." (PMID 20885957, 2010).